RN7SL180P (RNA, 7SL, cytoplasmic 180, pseudogene)
Gene: Miscellaneous RNA gene on chromosome 1 (62,072,448 to 62,072,741, forward strand). Ensembl gene ENSG00000242860.
Homologues: Orthologues: chimpanzee Metazoa_SRP (99% identical), macaque Metazoa_SRP (84% identical). Paralogues in human: RN7SL2 (81% identical), RN7SL1 (81% identical), RN7SL3 (80% identical), RN7SL786P (79% identical), RN7SL147P (79% identical), RN7SL122P (78% identical), RN7SL218P (78% identical), RN7SL220P (78% identical), RN7SL126P (78% identical), RN7SL478P (78% identical), RN7SL655P (78% identical), RN7SL18P (77% identical), and 702 more.